MCC (MCC regulator of Wnt signaling pathway)
Diseases named in the same sentence as MCC in open-access papers (continued):
Sharing a sentence is not in itself a finding about the gene and the disease.
Burkitt lymphoma (1 paper, 2015). A rare form of malignant mature B-cell non-Hodgkin lymphoma. "MCC expression is also significantly elevated in a variety of primary human B cell malignancies, including primary effusion lymphoma (PEL), centroblastic lymphoma (CBL), diffuse large B-cell lymphoma (DLBCL), Burkitt’s lymphoma (BL), and MM." (PMID 25960828, 2015).
Cirrhosis (1 paper, 2013). A chronic disorder of the liver in which liver tissue becomes scarred and is partially replaced by regenerative nodules and fibrotic tissue resulting in loss of liver function. "It is also interesting that MCC-L1-α was homozygous in donor 95, and therefore, MCC was almost certainly downregulated in the liver of this patient prior to HBV infection, i.e., preceding viral challenge, cirrhosis, and tumorigenesis." (PMID 23540693, 2013).
colon adenocarcinoma (1 paper, 2024). "Contrary to our findings, results from the TCGA-colon adenocarcinoma (COAD) database indicate that MCC expression is lower in the tumor tissues than in adjacent normal tissues." (PMID 39439956, 2024).
dengue (1 paper, 2025). "While their roles in dengue remain uncharacterized, MKI67’s association with proliferating cells (e.g., plasmablasts) and MCC’s NF-κB modulation by MCC suggest a potential involvement in viral replication or immune dysregulation." (PMID 41583452, 2025).
glioblastoma (1 paper, 2024). The most malignant astrocytic tumor (WHO grade IV). "Analysis of TCGA-GBM data revealed a significant association between MCC expression levels and clinical outcomes in glioblastoma patients." (PMID 39439956, 2024). "Importantly, we observed that high MCC expression was associated with poor prognosis in glioblastoma patients, highlighting its potential role in disease progression." (PMID 39439956, 2024). "The expression of MCC in human glioblastoma cell lines, normal brain tissue, and tumor tissues was analyzed, and experiments were performed to elucidate the function of MCC in glioblastoma cells." (PMID 39439956, 2024). "Based on our findings, MCC appears to play a pivotal role in oncogenesis, particularly in glioblastoma." (PMID 39439956, 2024). "Further work is required to define the detailed molecular mechanisms by which MCC modulates glioblastoma pathogenesis." (PMID 39439956, 2024). "Immunoblotting analysis using an anti-MCC antibody was performed to investigate the putative roles of MCC in glioblastoma." (PMID 39439956, 2024). "In glioblastoma patients, the MCC protein level, as revealed by Western blotting and IHC staining, was significantly higher than in normal tissues." (PMID 39439956, 2024). "This distinctive pattern suggests a complex role for MCC in cellular functions, potentially implicating MCC involvement in both nuclear and cytosolic processes relevant to glioblastoma pathology." (PMID 39439956, 2024). "In this study, the potential role of MCC in the pathophysiology of glioblastoma was investigated." (PMID 39439956, 2024). "We explored MCC expression in the glioblastoma database, patient samples, and cell lines." (PMID 39439956, 2024). "The expression levels of MCC in glioblastoma cell lines and human tumors were higher than in normal samples, but MCC knockdown cells exhibited elevated proliferation and migration, suggesting that MCC serves as a tumor suppressor in glioblastoma." (PMID 39439956, 2024). "MCC expression in glioblastoma tissues was increased compared with normal tissues." (PMID 39439956, 2024). "In glioblastoma, MCC is translocated from plasma membranes and organelles to the nucleus and then engages in an unknown form of signaling." (PMID 39439956, 2024). "This reduction in MCC methylation may explain the increased expression of MCC in grade 4 glioblastoma." (PMID 39439956, 2024). "The observed correlation between MCC expression levels and glioblastoma status indicates the MCC may serve as a new biomarker of glioblastoma." (PMID 39439956, 2024). "Additionally, this study identifies a nuclear localization of MCC in the glioblastoma cell line." (PMID 39439956, 2024). "Additionally, the bioinformatics data showed that the MCC expression level in glioblastoma tumors was higher than that in normal areas, which may be related to MCC gene methylation." (PMID 39439956, 2024). "Subsequently, the WST-1 and wound-healing assays revealed that the specific suppression of MCC translation significantly increased the proliferation and migration of siRNA-treated cells compared with control cells, suggesting that MCC might act as an anti-tumor agent in glioblastoma." (PMID 39439956, 2024). "Conversely, significant upregulation of MCC was observed in the following three cancer types: glioblastoma multiforme (GBM), pancreatic adenocarcinoma (PAAD), and thymoma (THYM)." (PMID 39439956, 2024). "Our study provides evidence that MCC, a tumor suppressor gene of CRC, might have a distinctive role in the pathophysiology of glioblastoma." (PMID 39439956, 2024).
Granuloma (1 paper, 2021). A compact, organized collection of mature mononuclear phagocytes, which may be but is not necessarily accompanied by accessory features such as necrosis. "Both MC phenotypes (MCT and MCC) were abundant at inflammatory (granulomas, pneumonia, vascular and airways walls) and fibrotic areas, but absent in the proximity of necrotic sites." (PMID 34021178, 2021).
Hypocalcemia (1 paper, 2025). An abnormally decreased calcium concentration in the blood. "Hence, we propose that hypocalcemia may directly or indirectly influence abnormal changes in MCC spontaneous activity in patients with ESHD, potentially impacting cognitive function through alterations in FC of the MCC." (PMID 40229685, 2025).
metastatic tumors (1 paper, 2009). "We took advantage of several established MCC cell lines with either high ATOH1 expression (MCC1 and MCC6, derived from less aggressive tumors) or low ATOH1 expression (MCC13, MCC14.2, and MCC26, derived from highly aggressive metastatic tumors)." (PMID 19243219, 2009).
multiple myeloma (1 paper, 2023). "With PHB2 as a hub of the MCC interaction network, MCC promotes cellular survival and tumorigenesis in multiple myeloma patients." (PMID 37190120, 2023).
non-Hodgkin lymphoma (1 paper, 2014). Distinct from Hodgkin lymphoma both morphologically and biologically, non-Hodgkin lymphoma (NHL) is characterized by the absence of Reed-Sternberg cells, can occur at any age, and usually presents as a localized or generalized lymphadenopathy associated with fever and weight loss. "Aberrant up-regulation of MCC also occurs in a variety of primary human B cell malignancies, including non-Hodgkin lymphoma (NHL) and MM." (PMID 25200342, 2014).
odontogenic cyst (1 paper, 2021). A cyst in the jaw that arises from tissues of tooth development.
rectal cancer (1 paper, 2022). A primary or metastatic malignant neoplasm that affects the rectum. "A subset of cancers display hypomethylation which is also associated with low MCC expression, particularly in rectal cancer, where CIMP is rare." (PMID 35740525, 2022).
tumor (24 papers, 2010 to 2025). "In a subgroup analysis of CRC, MCC was silenced by promoter hypermethylation and was associated with poor prognostic markers, such as high tumor grade and metastasis." (PMID 39439956, 2024). "MCC methylation was linked to adverse prognostic markers, high tumor grade, and metastasis in one patient cohort." (PMID 39439956, 2024). "After irinotecan treatment, tumor growth stabilized at 300 mm3 on day 18, and then started to decline faster for MCC-deficient than MCC expressing cells (p < 0.05)." (PMID 35740525, 2022). "In vitro knockdown of ALDH1A3 or associated genes such as FAM3C, MCC, PMEPA1, and IRS2 reduced tumor invasion, while in vivo reduction similarly curbed tumor growth and metastasis." (PMID 40781158, 2025). "Analysis of MCC expression in 31 cancer types from TCGA data revealed differential expression patterns between normal and tumor samples in each cancer category." (PMID 39439956, 2024). "MCC is emerging as a tumor suppressor involved in at least two cellular processes, the DNA damage response and cell–cell adhesion." (PMID 35740525, 2022). "Our study suggests that the loss of MCC expression, an individual gene strongly associated with CIMP, increases tumor sensitivity to irinotecan and PARPi separately, and even further in combination." (PMID 35740525, 2022). "MCC gene knockdown in tumor cells leads to increased DNA breaks and cell cycle perturbation after exposure to DNA damaging agents." (PMID 35740525, 2022). "Upregulation of MCC is associated malignant cell transformation for example in B-cells, and NEDD9 is associated to oncogenic signaling and tumor aggressiveness." (PMID 35565298, 2022). "EcN strains containing the p24-Lux-HS, p24-Lux-AT, p24-Lux-MCC, or p24-Lux control constructs were intravenously injected into a mouse tumor model for in vivo characterization." (PMID 30954530, 2019). "Additionally, cells with knocked down ALDH1A3 or the other key genes FAM3C, PMEPA1, and MCC showed reduced tumor xenograft growth and metastasis in mice, highlighting their role in tumor progression." (PMID 40781158, 2025). "Reassuringly, the resulting list includes several known colon tumor suppressors such as APC, TCF7L2, MCC, PTEN, and SMAD4." (PMID 29196508, 2017). "For samples of “other types” (MdC+McC), the amount of LMP7 subunit in adjacent tissue and Rpt6 subunit both in tumor and adjacent tissue, increased with metastasis progress from N0 to N3." (PMID 25329802, 2014). "A high deletion rate in chromosome 5q22.2 may explain poor clinical outcomes in young CRC patients, which is because the region contains several tumor suppressor genes, such as APC and MCC." (PMID 34702313, 2021). "Furthermore, overexpressing ALDH1A3 in ALDH1A3-negative PDAC cells (PANC-1/ALDH1A3OE) increased the expression of FAM3C, MCC, and PMEPA1, which was supported by our previous data demonstrating that ALDH1A3 overexpression in PANC-1 cells promoted tumor invasion in vitro." (PMID 40781158, 2025).
cancer (13 papers, 2010 to 2024). A tumor composed of atypical neoplastic, often pleomorphic cells that invade other tissues. "Down-regulation of MSH3 was also more frequent in MSI-H or CIMP-H cancers but the strongest association was observed with MCC methylation (p = 0.0001)." (PMID 34298744, 2021). "Results of Ingenuity analyses showed that 195 of the 333 (58.5%) MCC interactors in whole cell lysates and 91 of the 207 (43.96%) MCC interactors in mitochondria are associated with cancer." (PMID 25200342, 2014). "In parallel, loss of the MCC gene in a mouse model showed upregulation of IFNγ-induced GTPase superfamily in the absence of any external pathogen involvement in the inflamed colon and was restricted to immediate proximity of the damaged epithelial barrier leading to development of cancer." (PMID 34946170, 2021). "The MCC protein localizes to the nucleus, and is phosphorylated after radiation exposure, and ectopic MCC expression slows down cancer cell proliferation." (PMID 35740525, 2022). "If these results can be confirmed in further cancer cell lines, MCC alterations should be further evaluated for patient management." (PMID 35740525, 2022). "In the colon, 18% (50/272) of cancers had strong MCC CpG island hypermethylation, and these were diploid or showed copy number gain." (PMID 35740525, 2022). "MCC-methylated cancers include CpG island methylator phenotype (CIMP)-positive tumors that are potentially more responsive to irinotecan." (PMID 35740525, 2022). "Thus, MCC deletion sensitizes HCT116 cancer cells or MEFs to cell death in response to either SN38 or PARPi." (PMID 35740525, 2022). "Thus, MCC plays distinct roles via different signaling mechanisms in B cell malignancies versus other human cancers." (PMID 25200342, 2014). "Thus, the APC/MCC pair provided an excellent example to showcase our cross-species comparison strategy, utilizing the difference in the genomic location of orthologous genes in different species to distinguish between cancer driver and passenger alterations." (PMID 20707908, 2010). "In cell culture experiments, the deletion of MCC increased the responsiveness of cancer cells to the chemotherapy drug irinotecan (SN38), and this was further augmented by a targeted cancer drug, the PARP-inhibitor Olaparib." (PMID 35740525, 2022). "LATS2, MCC, DCC, RHOB, TRIM13, LIMD1, and GPC3 also strongly and positively regulated gene down-expression in cancer." (PMID 33580150, 2021). "MCC and CDKN2A methylation co-occurred in 57% (16/28) of the carcinomas positive for either marker in the colon but only 25% (2/8) in the rectum/rectosigmoid region." (PMID 34298744, 2021). "Therefore, when MCC activity is absent, cancer cells can accumulate DNA breaks which make them more sensitive to irinotecan and PARP-induced cell death." (PMID 35740525, 2022).
infection (2 papers, 2019 to 2023). The state of being infected such as from the introduction of a foreign agent such as serum, vaccine, antigenic substance or organism. "In sum, we anticipate the impaired antibacterial activity of EcN producing high amounts of McC (and conversely, the enhanced antibacterial activity of EcN producing low amounts of McC) would also be reflected in an active infection model, but this will be a subject of future experiments." (PMID 37930328, 2023). "g., MCc), the expression of virulence determinants, only required for host infection, should be, theoretically, not induced." (PMID 31711419, 2019).
MCC also shares sentences with these, for which no sentence is quoted: Airway obstruction (1 paper); amyotrophic lateral sclerosis (1); asthma (1); breast carcinoma (1); cervical squamous cell carcinoma (1); colon (1); colorectal (1); diffuse large B-cell lymphoma (1); endocervical adenocarcinoma (1); endometrial cancer (1); endothelial dysfunction (1); familial colorectal cancer (1); glomerular diseases (1); head and neck squamous cell carcinoma (1); Hirschsprung disease (1); lung adenocarcinoma (1); lung carcinoma (1); malaria (1); ovarian serous cystadenocarcinoma (1); pancreatic adenocarcinoma (1); pneumonia (1); primary effusion lymphoma (1); prostate carcinoma (1); thymoma (1); tobacco use disorder (1); uterine carcinosarcoma (1); Winchester syndrome (1).